RAG1 (recombination activating 1)
Diseases named in the same sentence as RAG1 in open-access papers (continued):
Sharing a sentence is not in itself a finding about the gene and the disease.
infection (continued). "Similarly, in spleens from LCMV-infected RAG1 KO mice, there were no significant changes for TNF, IL-1β and IL-6 mRNAs post infection." (PMID 32310998, 2020). "In RAG1 KO mice, neither IFN-α or IFN-β were detectable following infection any timepoint analyzed." (PMID 32310998, 2020). "When naïve rag1−/− or rag1+/+ zebra fish of 6 months of age were infected by bath immersion with 104 pfu/ml of SVCV, there were neither infection symptoms nor deaths for the first 2 days after infection." (PMID 28243233, 2017). "An absence of IL-17A or the IL-1 receptor was associated with reduced neutrophil recruitment to the site of infection; and clearance of GAS was significantly attenuated in IL-17A−/− mice and Rag1−/− mice (that lack mature lymphocytes) but not in mice deficient for the IL-1 receptor." (PMID 27241677, 2016). "There were no clinical signs of illness (e.g., lethargy, ruffled fur) following SC or FP inoculation of RAG1-/- or congenic C57BL/6J mice with either vaccine strain or wt CHIKV, and no change in weight was identified after SC infection regardless of the virus strain." (PMID 26115459, 2015). "Notably, reconstitution of Rag1-/- mice with CD4+, but not CD8+ T cells largely restored the IEC hyper-proliferative response during infection." (PMID 26285214, 2015). "Interestingly, adoptive transfer of nonskewed bulk CD4+ or Th0 T cells were also protective in Rag1–/– mice, and both acquired a robust IFN-γ signature in the brain, suggesting that CD4+ T cell populations can be shaped by the infection milieu to provide benefit." (PMID 39989461, 2025). "However, none of these mediators was differentially modulated in RAG-1−/− and RAG-1−/−/OT-I and RAG-1−/−/OT-II mice compared with WT mice, excluding the possibility that cytokines released by T cells or a latent state of infection as being responsible for the behavioral changes observed." (PMID 23838891, 2013).
cancer (28 papers, 2011 to 2025). A tumor composed of atypical neoplastic, often pleomorphic cells that invade other tissues. "There is a larger proportion of somatic mutation (e.g., cancer) in these databases compared to germline mutation for RAG1/2." (PMID 37854700, 2023). "The use of the Rag1 knock-out strain and Pmel-1 in this study removed the benefit of a diverse arsenal of endogenous T cells, thus promoting cancer immune escape from single epitope-specific Pmel-1." (PMID 36497152, 2022). "Their developmental functions can explain the early-onset of RAG1/2 and PGBD5-expressing cancers, but can also promote mutations in older individuals, simply at reduced relative incidence." (PMID 32411637, 2020). "Rag1−/− mice mice (on a BALB/c background) have been used for cancer allograft and xenograft studies for prostate cancer." (PMID 28352127, 2017). "We conclude that Rag1−/− mice are an appropriate and novel xenograft model for studying the relationship between cancer and hyperinsulinaemia." (PMID 28352127, 2017). "We extended our evaluation to Rag1−/− mice deprived of a functional adaptive immune system, thus mimicking an immune compromised state of cancer patients." (PMID 26981777, 2016). "However, there is an elevated level of missense mutation in some cancer types at ZNF positions 9 and 11 adjacent to the HR “ACA” sequence, similar to that found in RAG1 cleavage substrates." (PMID 37164635, 2023). "In our hypothesis, mutations induced by developmental mutators such as RAG1/2 and PGBD5 that happen early in life lead to specific forms of somatic mosaicism and the risk of early onset cancers." (PMID 32411637, 2020). "Recent studies have shown that the high expression of RAG1 is a potential driver of oncogenesis in B-cell ALL, and the aberrant activity of RAG1/2 is associated with the promotion of lymphocytic malignancies due to chromosomal translocations and DNA deletions in cancer genes." (PMID 36497424, 2022). "In addition, it appears that transcription activators may regulate the gene expression of the recombination activating gene 1 (RAG1) in cancer cells." (PMID 27649156, 2016). "To explore this goal, we employed PK5L1940 and BRAF cancer cells to compare results in both KRAS and BRAF mutant models in RAG1 KO mice." (PMID 37415974, 2023). "We observed lung metastasis 3 weeks after the injection of human cancer cells, MDAMB231 or MCF7, into mice with Rag1-/- background." (PMID 37620307, 2023). "Upregulation of MS4A1, IGLL1, RAG1, and SEMA3A resulted in significantly decreased survival in pediatric cancer patients." (PMID 36497424, 2022). "Upregulated expressions of E2A, FOXO1, or FOXP1 enhanced RAG1 expression, while silencing of E2A, FOXO1, or FOXP1 decreased RAG1 expression in the cancer cells." (PMID 34226529, 2021). "RAG1 and RAG2, the essential enzymes for V(D)J recombination, were also detected in cancer samples, whereas AID, an enzyme required for class switch and somatic hypermutation, was only detected in the two poorly differentiated cell lines (LOVO and HCT116)." (PMID 23133595, 2012). "We also confirmed the expression of RAG1 and RAG2 in these cancer cell lines." (PMID 21655267, 2011). "Recombination activating gene 1 (RAG1) and RAG2, which are essential enzymes for initiating variable-diversity-joining segment recombination, have also been found to be expressed in cancer cells." (PMID 21655267, 2011). "Although expression of Rag1 and Rag2 transcripts have been reported in a variety of non-lymphoid cells, including different cancer cell types, epithelial cells and neurons, to our knowledge, no functional role for these enzymes have been identified in non-lymphoid cells." (PMID 29755449, 2018). "Interestingly, we found that BNT162b2 had a similar anti-cancer effect in the μMT mouse model in comparison to that in WT mice, however, it had no obvious therapeutic effects in Rag1−/− mice, indicating that the BNT162b2-based cancer therapy was predominantly T cell-dependent." (PMID 39743545, 2025).
inflammation (7 papers, 2016 to 2025). Aberrant reaction of the microcirculation characterized by movement of fluid and leukocytes from the blood into extravascular tissues. "To assess the relative role of innate versus adaptive immunity in the context of spontaneous skin and lung inflammation caused by filaggrin deficiency, we crossed Flgft/ft and Rag1−/− mice, generating T cell– and B cell–deficient Rag1−/−Flgft/ft mice." (PMID 26299987, 2016). "In accordance with this, Gpr109a-/-Rag1-/- mice developed spontaneous colonic inflammation and had increased ILC3s in the gut relative to Rag1-/- mice especially IL-17-producing ILC3s." (PMID 33193381, 2020). "Using a mouse model of IL-33-induced lung inflammation, the pathophysiological in vivo relevance of this interaction could be strengthened: blocking the CD11a subunit of the ligand LFA-1 resulted in decreased signs of lung inflammation in immunodeficient Rag1−/− mice." (PMID 32655549, 2020). "Ovalbumin (OVA)-specific OT-II; Cas9 CD4+ T cells were activated and transduced with the lipid-targeting sgRNA library and adoptively transferred into Rag1−/− mice, which were then intranasally sensitized with OVA protein to promote lung inflammation." (PMID 40204636, 2025). "Oral inflammation in Rag1−/− mice was induced by the adoptive transfer of CD4+CD25−CD45Rb (high) T cells, and co-transfer of Treg cells with CD4+CD25−CD45Rb (high) T cells inhibited the development of oral inflammation in the mice." (PMID 38515628, 2024).
blood cancer (2 papers, 2022 to 2026). "In the case of RAG1/2 and PGBD5, their dysregulation causes somatic oncogenic DNA rearrangements in blood cancers and solid tumors affecting children and young adults." (PMID 41533792, 2026). "NGS data from normal B-cell and T-cell developmental stages and blood cancer samples have been analyzed for the expression of miRNAs against RAG1 (1,173 against human RAG1 and 749 against mouse RAG1)." (PMID 35401578, 2022).
colon (2 papers, 2020 to 2023). "In our study, RAG1 KO mice were utilized to exmaine the specific impact of MK2 in CD8+ T cells on GI tumors." (PMID 37415974, 2023). "Overall, histopathologically assessed parameters summarized in the histology score underscore and further extend the results obtained during endoscopic evaluation that Rag1−/− mice lacking IRF4 expression are largely protected from T cell mediated colon inflammation." (PMID 33584655, 2020).
hematologic malignancies (2 papers, 2023 to 2024). "Apart from the regulation of cell-cycle arrest, FOXO1 is also a potent transcriptional activator of RAG1, which is critical for tumorigenesis and survival in hematological malignancies." (PMID 36675119, 2023).
adenocarcinoma (1 paper, 2017). A common cancer characterized by the presence of malignant glandular cells. "Unsupervised clustering analysis showed a distinct cytokine profile in normal prostate (WT and RAG1-/-) and adenocarcinoma containing prostates (Hi-Myc, and Hi-MycRAG1-/-> 24 weeks of age)." (PMID 29212195, 2017).
hematopoietic neoplasms (1 paper, 2024). "However, in RAG1/RAG2-deficient patients, as well as in overall SCID patients, hematopoietic neoplasms are extremely rare." (PMID 39026935, 2024).
infectious disease (1 paper, 2019). A disorder directly resulting from the presence and activity of a microbial, viral, or parasitic agent in humans. "Rag1−/− zebrafish (Danio rerio) are viable and reach adulthood without obvious signs of infectious disease in standard nonsterile conditions, suggesting that innate immunity could be enhanced to compensate for the lack of adaptive immunity." (PMID 31348603, 2019).
RAG1 also shares sentences with these, for which no sentence is quoted: combined immunodeficiency (16 papers); DiGeorge syndrome (4); depression (3); genetic disorders (3); Hyperglycemia (3); alopecia (2); cervical cancer (2); CHARGE syndrome (2); enteropathy (2); fibrosarcoma (2); intestinal disease (2); Kawasaki disease (2); liver cancer (2); multiple myeloma (2); neuroblastoma (2); neurological disease (2); Opportunistic infection (2); pancreatic cancer (2); Peritoneal Fibrosis (2); X-linked Severe Combined Immunodeficiency (2); –Aldrich syndrome (2); acute leukemia (1); adenovirus infection (1); albinism (1); allergic asthma (1); Alport syndrome (1); Alzheimer disease (1); aplastic anemia (1); arteriosclerosis (1); atopic dermatitis (1).
A further 84 diseases each share a sentence with RAG1 in 1 paper.